ENSG00000275942
Gene: Miscellaneous RNA gene on chromosome 22 (26,672,164 to 26,672,248, forward strand). Ensembl gene ENSG00000275942.
Gene Ontology:
Biological process: cell fate specification
Cellular component: nucleus